TNF (tumor necrosis factor)
Diseases named in the same sentence as TNF in open-access papers (continued):
Sharing a sentence is not in itself a finding about the gene and the disease.
colitis (continued). "We observed significant increases in colonic IL-6, IL-1β, MCP-1, and TNF-α levels in colitis, which were effectively reduced by CBD and HU308 treatments." (PMID 39682761, 2024). "By preventing iron sequestration, butyrate not only mitigates colitis‐induced anemia but also reduces TNF‐α production in macrophages." (PMID 38235606, 2024). "Among groups subjected to the induction of experimental colitis, the most intensive increase in local concentrations of TNFα at the peak of the disease was recorded in PC groups for both strains." (PMID 38892639, 2024). "In the colitis mice, the expression of IL-6, TNF-α, and IL-1β in the colon tissue was significantly increased after treatment with HPAD or HSAD." (PMID 38233383, 2024). "Previous research has shown that TNF-α-primed canine AMSCs enhance immunomodulatory effects in a DSS-colitis model by increasing M2 macrophages in the colon." (PMID 39595338, 2024). "In our study, SP suppressed the activation of the cGAS-STING pathway in a dose-dependent manner, both in colitis mice and in TNF-α-induced colonic epithelial cells." (PMID 38725846, 2024). "TNF-α levels were significantly elevated in the colitis vehicle group compared to the healthy controls (p < 0.0001)." (PMID 39682761, 2024). "SPAK is a signal transducer of environmental and cellular stress signals, including NF‐κB‐dependent inflammationInterferon (IFN)‐γand TNF‐αstimulate SPAK signaling in an NF‐κB‐dependent manner to increase epithelial transport in experimental colitis." (PMID 39450988, 2024). "An analysis of TNF-α expression, an inflammation indicator, showed that the TNF-α level was elevated in the control mice 4 and 12 days after zymosan-induced colitis." (PMID 38892616, 2024). "Treatment with SFN significantly reduced the concentrations of pro-inflammatory cytokines IL-6, IFN-γ and TNF-α in mice with DSS-induced colitis." (PMID 39517291, 2024). "Treatment of DCs with PSA-containing MVs prevented trinitrobenzene sulfonic acid (TNBS)-induced colitis in mice via suppression of the proinflammatory cytokines, TNF-α and IL-17, and increased secretion of IL-10." (PMID 38666762, 2024). "We also explored the effect and underlying mechanism of Cyn in inhibiting IEC apoptosis on intestinal barrier function and colitis using both the TNF-α-induced colonic organoid model and the TNBS-induced mouse model." (PMID 39902073, 2024). "The current study certificates that quercitrin alleviates the colitis model by enhancing tumor necrosis factor α (TNF-α) and interleukin 1β (IL-1β) expressions." (PMID 38397537, 2024). "Our data revealed a significant upregulation of IL-1β, IL-2, and TNF-α levels in the colitis mice model." (PMID 38613088, 2024). "Further investigations revealed that the increased expression of GP2 in the pancreas was closely correlated with tumor necrosis factor-α (TNF-α), an inflammatory agent that is markedly elevated in cases of colitis." (PMID 38170255, 2024). "They tested this concept using ELISA and discovered that IL-1β, IL-6, and TNF-α were significantly induced in the colon tissue of DSS-induced colitis mice, indicating a potent anti-inflammatory mechanism." (PMID 39323474, 2024). "The present study, along with previous works, showed an activated Notch-Hes1 pathway in TNF-α-treated Caco-2 cells or mice with DSS-induced colitis; however, the activation of the Notch pathway triggered by inflammation failed to rescue TJ injury." (PMID 39130644, 2024). "When acute colitis is induced, the expression of TNF-α and IFN-γ increases the factors related to Th1 and Th17, and inflammatory responses are generated." (PMID 38611304, 2024). "In ICI colitis, an inflammatory macrophage population responds to and produces TNFα and other chemokines, which likely results in the recruitment of additional T cells from the blood into the colon, further exacerbating colitis." (PMID 38995215, 2024).
colitis (continued). "For instance, colitis induced by ICIs can be effectively managed with a single dose of infliximab, a chimeric monoclonal antibody targeting tumor necrosis factor alpha (TNFα)." (PMID 39113705, 2024). "For example, a previous study reported that ZnO nanoparticles reduced the elevated concentrations of IL-1β and TNF-α in a model of DSS-induced colitis." (PMID 38998031, 2024). "Studies demonstrate that curcumin suppresses TNF-α in colitis models, leading to reduced intestinal inflammation and improved clinical outcomes." (PMID 39597805, 2024). "MRO-SeNPs successfully reduced colitis by reducing pro-inflammatory mediators such as IL-1ß, IL-6, TNF-α, IL-12, and MCP-1 in colon tissues and exerting significant antioxidant activity." (PMID 38796570, 2024). "Taken together, priming with colitis tissue homogenate enhanced the immunomodulatory capacity of cADSCs as much as priming with a combination of TNF-α and IFN-γ, a priming method that is well known to enhance the immunosuppressive capacity of MSCs." (PMID 39176394, 2024). "The latest research shows that secoisolariciresinol diglucoside alleviates colitis by inhibiting NLRP1 inflammasomes, correlating with reduced IL-1β, IL-18, and TNF-α levels in DSS-induced colitis mice." (PMID 38455052, 2024). "DSS in mice appear to induce a clear interferon alpha and gamma response as well as an interleukin 6 (IL-6) and tumor necrosis factor alpha (TNF-a) response that is in line with the signatures typically observed in human colitis." (PMID 38249103, 2024). "HFD feeding resulted in colitis: it elevated myeloperoxidase, TNF-α, IL-1β, and IL-6 levels, NF-κB activation (p-p65/p65), and NF-κB+CD11c+ cell number and decreased IL-10 and SIRT1 levels and AMPK activation (p-AMPK/AMPK) in the colon." (PMID 39599597, 2024). "Using naive T cells extracted from hTNF‐KI donor animals, they created a mouse colitis model that was exclusively dependent on human TNF expression in the progeny of hTNF‐KI mice bred with Rag1−/− mice." (PMID 38533646, 2024). "Several studies have suggested the anti-inflammatory functions of NA in various diseases, such as colitis and Parkinson's disease, especially in reducing the release of pro-inflammatory cytokines, such as TNF-α, IL-6 and NF-κB with therapeutic effects." (PMID 39364738, 2024). "In patients who are refractory to corticotherapy, some irAEs, such as colitis, can be treated with a bolus of infliximab, an anti-Tumor Necrosis Factor α (TNF) antibody." (PMID 39136013, 2024). "S. cerevisiae strains exhibited in vivo reduction of pro-inflammatory cytokines IL-1β, IL-6 and TNF-α and promoted the expression of the anti-inflammatory cytokine IL-10 in colitis mice." (PMID 39628717, 2024). "During the inflammatory response caused by colitis-induced model or IBD, IL-1β along with other proinflammatory cytokines such as TNF-α and IL-6 orchestrate the inflammatory response within the lamina propria." (PMID 38323035, 2024). "Butyrate acid and propanoic acid, key components of XYKJP, play a crucial role in reducing colonic mucosal injury and decreasing IL-1β, TNF-α, and IL-6 in the colitis mouse model." (PMID 39133435, 2024). "In this study, both the HWB and LWB treatments demonstrated a significant reduction in pro-inflammatory factors (TNF-α, IL-6, and IL-1β) in the colon tissues of colitis mice." (PMID 38254526, 2024). "In a murine study, L-glutamine supplementation improved DSS-induced colitis, decreased macroscopic damage, decreased TNF-α production in parallel, improved the disease activity index, and induced MKP-1, which inhibited cytosolic phospholipase A2 (cPLA2)." (PMID 39451206, 2024). "NK109 also suppressed the LPS-induced expression of colonic myeloperoxidase, TNF-α, and IL-1β expression, resulting in the attenuation of colitis." (PMID 39203872, 2024). "EZH2 reduction directly stimulates TRAF2/5 expression to enhance TNFα-induced NF-κB signaling, and promote inflammation and apoptosis in colitis." (PMID 39588368, 2024).
colitis (continued). "Here we report the case of a gentleman with newly diagnosed T1D whose glycaemic control and insulin requirement improved whilst on a five year infusion programme of infliximab, a monoclonal antibody against TNF-alpha, for colitis." (PMID 39252097, 2024). "The downregulated expressions of inflammatory cytokines such as TNF-α and IL-1β were noticed to recover the colonic ZO-1 protein abundance in the colitis mice." (PMID 39616350, 2024). "In this study, animals with colitis induced by AA displayed a notable increase in the concentration of both IL-1β and TNF-α, assessed through ELISA and immunohistochemistry, as reported by others." (PMID 39199130, 2024). "Wang and colleagues examined the impact of VSL#3, a probiotic, on NF-κB and TNF-α in rats with colitis." (PMID 39323474, 2024). "The leaf methanol extract of M. longifolia, together with its major constituent eucalyptol, have protective effects against acetic acid-induced colitis in rats by significantly reducing the up-relation of serum IL-6 and TNF-α levels." (PMID 38310564, 2024). "IL-10 is able to suppress T cell-mediated immune response and ameliorate colitis by inhibiting antigen presenting cells, and downregulate IL-1β, IL-6, and TNF-α secreted by macrophages and T cells." (PMID 38397562, 2024). "Apigenin treatment inhibited colon damage, MPO activity, and the production of IL-1β, TNF-α, and IL-6 in DSS-induced colitis, as well as the NF-κB and STAT3 pathways in colitis-associated colon cancer tissues in mice." (PMID 39451206, 2024). "Concentrations of the cytokines IL-23, IL-17, IL-6, TNF,and IL-1β were higher in the colon from the colitis group comparedto the control groups, confirming the presence of colitis." (PMID 39022369, 2024). "Melatonin has also been shown to decrease MMP-9 and MMP-2 activities in models of ethanol-induced gastric ulcers and experimental colitis, with reduced tumor necrosis factor-alpha (TNF-α) expression." (PMID 39456451, 2024). "TNF-α plays a crucial role in mediating inflammation in colitis, and it has been one of the targets for colitis treatment." (PMID 39770982, 2024). "The reasons for VDZ treatment were steroid-dependent colitis in 19 (26.0%), steroid-refractory colitis in 6 (8.2%), failure or intolerance to anti-TNF therapy in 10 (13.7%), and clinician/patient preference in 38 (52.1%) patients." (PMID 38968537, 2024). "TNF-alpha blockade has been a ubiquitous strategy for management of irAEs, especially in colitis and arthritis." (PMID 39737191, 2024). "There was an increase in TNF-α levels in the colitis group compared to the control group, but this increase was not statistically significant." (PMID 39105785, 2024). "boulardii combination (109 CFU/ml and 107 CFU/ml) significantly reduced the DAI, inhibited colitis, lowered IL-1β and TNF-α production, and significantly improved the levels of butyric acid and isobutyric acid." (PMID 38835484, 2024). "In vivo, strains of B. dentium were able to relieve colitis symptoms in a DSS stimulated mice model, decreased weight loss and levels of TNF, IL-8 and IL-6 inflammatory markers in a TNBS-induced colitis mice model." (PMID 38951788, 2024). "TNF-α, IL-1b, and IL-6 have been shown to promote colonic inflammation, with TNF-α causing damage to the intestinal mechanical barrier, and IL-10 and IL-12, which are anti-inflammatory cytokines, which can inhibit inflammation." (PMID 39723143, 2024). "These indications were significantly lower in the LF + H + DSS group, demonstrating that L. fermentum CQPC04 controls TNF-α and IFN-γ expression in colitis animals, minimizing damage caused by inflammation." (PMID 39323474, 2024). "Only the TNFα level in the control group of animals subjected to feed containing low-molar mass OBG was higher than in the relevant animal group with colitis." (PMID 39125425, 2024).
colitis (continued). "KEGG pathway analysis showed that immune-related pathways, including the IL-17, TNF, and NLR signaling pathways were the major pathways associated with MyD88 inhibition in DSS-induced colitis." (PMID 38946731, 2024). "Both naive cADSCs and cADSCs primed with any condition reduced F4/80+ CD80+ M1 macrophages, which were drastically increased by colitis induction, but cADSCs primed with TNF-α+IFN-γ or colon homogenate in particular significantly and markedly reduced them." (PMID 39176394, 2024). "In conclusion, targeting the NF-κB and MAPK signaling pathways to reduce the expression of inflammation-related genes and proteins, such as IL-6 and TNF-α, represents an effective strategy for treating colitis." (PMID 39323474, 2024). "It is established that TNF‐α, IL‐6, and IL‐1β are key proinflammatory cytokines involved in the onset of colitis, and IL‐10, an anti‐inflammatory cytokine, increases following Res administration in IBD patients." (PMID 38372468, 2024). "In parallel, the phosphorylation of NF-κB p65 and IκBα (inhibitor of NF-κB) was decreased following the administration of over-expressed miR-146a EVs, leading to inhibited secretion of TNF-α, IL-6 and IL-1β and thus ameliorated colitis." (PMID 38323035, 2024). "Curcumin significantly reduces TNF-α levels in various disease models, including colitis, arthritis, and metabolic disorders." (PMID 39597805, 2024). "In a different animal study, treatment with pioglitazone (another PPARγ agonist) improved DSS-induced colitis, disease activity, and histology and decreased TNF-α secretion in mice in an annexin-A1-dependent manner." (PMID 39451206, 2024). "Many experimental studies have shown that whey protein and soy protein can significantly inhibit the expression of TNF-α in the colon of colitis animals, improve intestinal mucosal permeability, and reduce the score of colon inflammation." (PMID 39064745, 2024). "Although TNF‐α neutralization significantly mitigated colitis development in FPNMWT mice, the therapeutic efficacy was compromised in FPNMKO mice, suggesting that macrophage iron overload limits the effect of αTNF‐α therapy." (PMID 38235606, 2024). "In IBD patients, the levels of IL-6 and TNF-α production are significantly greater in the serum and tissues, and enhanced local or systemic inflammation disrupts TJs and leads to worsened colitis." (PMID 38790680, 2024). "L. plantarum HNU082 and B. adolescentis also attenuated the inflammatory response in a DSS-induced colitis by downregulating TNF-α and IL-1β while upregulating IL-10." (PMID 37639209, 2024). "TNF-α plays a crucial role in promoting intestinal epithelial mucosal injury in colitis as a pro-inflammatory factor that initiates an immune response to harmful stimuli." (PMID 38254526, 2024). "Indigo Naturalis (IN) notably improved colitis in mice by enhancing colon tissue structure, reducing pro-inflammatory cytokines (IL-6, IL-8, TNF-a), and increasing anti-inflammatory cytokine IL-10." (PMID 39411430, 2024). "The colon of mice with DSS-induced colitis expresses high levels of TNF-α and IFN-γ compared with that of healthy mice, but at picogram levels." (PMID 39176394, 2024). "A significant decrease in mRNA expression of colon TNF-alpha, IL-1, and IL-6 was dominantly observed in dextran sulfate sodium-induced colitis in mice with a gamma-oryzanol diet (100 mg/kg body weight/day for 18 days) when compared with a normal food diet." (PMID 38337717, 2024). "UD extract was found effective in reducing colitis clinical signs, as revealed by the significant reduction in inflammatory markers IL-1β and TNF-α in treated animals." (PMID 39000608, 2024). "Studies have shown that icariin can alleviate DSS-induced colitis by inhibiting NF-κB signaling pathway-mediated TNF-α and IL-6 expression." (PMID 38645561, 2024). "The levels of the inflammatory factors IL-1β, IL-6, and TNFα in mouse intestinal tissue were studied to evaluate the extent of colitis-related inflammation." (PMID 39250508, 2024).
colitis (continued). "ATG16L1-deficieny in myeloid cells or DCs resulted in a similar phenotype than Tlr7-/- mice, with increased susceptibility to DSS colitis, increased disease activity index, histoscores, and increased secretion of IFN-γ and TNF-α." (PMID 39464882, 2024). "In colitis models, resveratrol administration resulted in decreased TNF-α expression, reduction in inflammatory cell infiltration, and improved histological outcomes." (PMID 39597805, 2024). "Significantly higher levels of IL-6, IL-1β and TNF-α were detected in mice with colitis compared to control mice." (PMID 39165355, 2024). "In mice with colitis, treatment with a probiotic mixture significantly decreased the concentration of TNF-α compared to the untreated colitis mice (p < 0.001)." (PMID 39201260, 2024). "first reported that ginsenoside Rg1 was capable of protecting against DSS-induced mouse colitis through markedly downregulating proinflammatory cytokines secretion (IL-1β and TNF-α)." (PMID 38698858, 2024). "Here, we evaluated the effects of Raf on inflammation using a DSS-induced colitis mouse model, focusing on serum levels of IL-2, IL-1β, TNF-α, and IL-6." (PMID 38928791, 2024). "In models of colitis, Hericium erinaceus has shown significant downregulation of TNF-α, alongside reductions in IL-6 and IL-1β, reflecting its role in mitigating inflammation similarly to EPA and GLA combinations." (PMID 39597805, 2024). "Treatment with MV significantly reduced the releases of proinflammatory factors TNF-α, IL-1β, and increased the levels of anti-inflammatory factors IL-2 in mice with colitis, indicating its good anti-inflammatory effects." (PMID 38773576, 2024). "In the 2% DSS-induced colitis-mouse model, Trp administration (100 mg/kg) led to a significant decrease in TNF-α and increase in IL-10 in the serum as well as a significant decrease in the inflammation score." (PMID 38542428, 2024). "This reinforces the potential for combining multiple natural agents to synergistically target TNF-α and other pro-inflammatory mediators in chronic inflammatory diseases such as colitis." (PMID 39597805, 2024). "Colitis is a chronic inflammatory digestive condition of the colon’s inner lining, commonly recognized by measurement of fecal IL-1β and mucosal TNF-α." (PMID 39000608, 2024). "In this study, after administering Ento-PB to rats with OXZ-induced colitis, the expression levels of IL-13 and TNF-α significantly decreased, while the expression levels of IL-4, IL-10, and EGF sharply increased." (PMID 39230095, 2024). "The extract of Hericium erinaceus, or lion’s mane mushroom, has demonstrated an ability to reduce TNF-α and pro-inflammatory cytokines in experimental models, particularly in neural and colitis studies." (PMID 39597805, 2024). "We also observed increased levels of inflammatory cytokines TNF-α, IL-1β, and IL-6 in two colitis groups." (PMID 39118149, 2024). "This study revealed that L. gasseri ATCC33323 can ameliorate physiological damage in mice with colitis, reduce the extent of colitis, decrease inflammatory cell infiltration, and decrease the levels of the inflammatory factors IL-1β, IL-6, and TNFα." (PMID 39250508, 2024). "Cytokine plasma levels currently used to monitor DSS colitis (TNFα, IL6, IL10 and IL17) were dosed at 3 (baseline) and 5.5 months to evaluate systemic inflammation." (PMID 38773640, 2024). "More importantly, combined SFELNVs and CX5461 alleviated mice colitis by inhibiting pro-inflammatory factors (TNF-α, IL-1β, and IL-6) expression and promoting M2 macrophage polarization." (PMID 39379937, 2024). "Similar to that in the colonic tissues of acute colitis model mice, IL-6 and TNF-α expression was significantly increased in the colonic tissues of chronic colitis model mice." (PMID 39512421, 2024).